STAT3 (signal transducer and activator of transcription 3)
Diseases named in the same sentence as STAT3 in open-access papers (continued):
Sharing a sentence is not in itself a finding about the gene and the disease.
cancer (continued). "The activation of STAT3 at Tyr705 is linked to malignant cancer behaviors, including cell proliferation, migration, invasion and metastasis." (PMID 30618745, 2018). "STAT3 is also an important regulator of immune cell function, which has been previously linked to cancer." (PMID 29928478, 2018). "As cancers harboring K171-mutated IKKβ are likely to also exhibit activated STAT3 and p44/42 MAPK (Erk1/2), this suggests the possibility of using MAPK (Erk1/2) and JAK inhibitors, or specific ubiquitination inhibitors." (PMID 30335863, 2018). "To gain further insights into the role of a prognostic marker, we next investigated the association of STAT3 expression and OS in various cancers, the prognostic value of STAT3 mRNA expression was assessed using the Kaplan-Meier Plotter and PrognoScan." (PMID 29423040, 2018). "F. nucleatum also acts as persistent anchor of biofilms in the cancer tissue and subsequent E-cadherin loss activates Wnt signaling and IL-6 driven Stat3 activation." (PMID 30412600, 2018). "The IL6/STAT3 signaling pathway has been implicated in cancer cachexia, a multifactorial condition that presents with skeletal muscle wasting, adipose tissue atrophy, and anorexia." (PMID 30072615, 2018). "High STAT3 expression in the nucleus was also associated with a significantly higher risk of both disease progression (p = 0.003) and cancer-specific mortality (p = 0.034)." (PMID 30091994, 2018). "In the last decade, several anti-STAT3 compounds have been identified to inhibit cancer-associated proliferation, inflammation and chemotherapy resistance." (PMID 29682172, 2018). "Correspondingly, previous report showed that IL-6 treatment enhanced CD44 (variant 6) expression in cancer cells via STAT3 activation." (PMID 30473835, 2018). "The STAT3 pathway is mainly associated with survival and proliferation and often constitutively activated by phosphorylation at Tyr705 in cancer, also in osteosarcoma." (PMID 29636527, 2018). "In line with our study, recent evidence has also implicated that the JAK2/STAT3 signaling pathway from a regulatory perspective due to its involvement in various fundamental biological processes as well as the pathogenesis of cancer." (PMID 30123088, 2018). "VEGF/VEGFR2 axis-established autocrine loop consisting of STAT3, Myc and Sox2 which implicated in enhancement of cancer stem-like cell phenotype in TNBC." (PMID 29455658, 2018). "MDSCs produce IL-6, which promotes the phosphorylation of STAT3, and the production of nitric oxide, in turn activating Notch signal, which causes prolonged STAT3 activation and supports cancer cell stemness." (PMID 30154786, 2018). "Our findings reveal a retromer-dependent mechanism for STAT3 activation and inflammation-associated cancer development." (PMID 30143645, 2018). "It is well known that MDR1, EGFR, and STAT3 are in significant associations with the multidrug resistant of cancer cells." (PMID 29872398, 2018). "Aberrant STAT3 signaling is frequently linked to cancer cell proliferation, survival, metastasis, tumor immunosuppression, and angiogenesis." (PMID 29921758, 2018). "Aberrant activations of the STAT3 (signal transducer and activator of transcription 3) signaling pathway are associated with cancer and inflammatory diseases." (PMID 29921758, 2018). "STAT3 activation has been found to be associated with cancer progression including survival, proliferation, metastasis, and chemoresistance." (PMID 29576846, 2018). "Cancers harboring K171-mutated IKKβ are likely to also exhibit activated STAT3 and p44/42 MAPK (Erk1/2), suggesting the possibility of using MAPK (Erk1/2) and JAK inhibitors, or specific ubiquitination inhibitors." (PMID 30335863, 2018). "Although IL-6-mediated activation of the signal transduction and activator of transcription 3 (STAT3) axis is involved in inflammation and cancer, the role of STAT3 in Helicobacter-associated gastric inflammation and carcinogenesis is unclear." (PMID 29849601, 2018).
cancer (continued). "Together, these data verify that exosomal gp130 is indeed causative for the observed STAT3 signaling, IL-6 secretion, morphological changes, and enhanced survival of BMDMs in response to cancer-derived exosomes." (PMID 29867925, 2018). "The identification of the IL6/JAK/STAT3 signaling cascade as cooperative partner in HH/GLI‐associated cancers provides a new rationale for evaluating combined HH‐IL6 targeting in BCC to improve the therapeutic efficacy of SMO inhibitor treatments." (PMID 29987839, 2018). "Growing evidence showed that the curative effects of CTS on various cancers are accomplished mainly through modulating STAT3, so our results supplied new data to clarify the underlying mechanism of CTS on various cancers." (PMID 30094960, 2018). "STAT3 is frequently found activated in several cancers including EGFR wild type as well as EGFR-mutated NSCLC." (PMID 29576846, 2018). "Chronically elevated STAT3 activity can lead to downstream activation of myostatin and the ubiquitin proteasome system, as observed in cancer cachexia models, causing protein degradation and loss of muscle mass." (PMID 29897957, 2018). "During chronic inflammation, NF-κB and STAT3 are central regulators of liver inflammation and are frequently associated with increased risk of cancer." (PMID 30279347, 2018). "Deregulated STAT3 signaling is an oncogenic driver and is associated with virus-induced complications, including cancers." (PMID 29543893, 2018). "Overall, these studies demonstrate that in addition to being activated in HPV-associated cancers, STAT3 is critically important for the productive HPV life cycle and a possible target for therapeutic intervention." (PMID 29630659, 2018). "Previous reports have clarified that abnormalities in JAK2/STAT3 signaling are associated with oncogenesis in several types of cancer." (PMID 29242197, 2018). "For example, in cancer cachexia, activated STAT3 has been shown to initiate skeletal muscle protein loss via the stimulation of caspases, myostatin and the ubiquitin-proteasome system." (PMID 29897957, 2018). "This has important consequences for the host, since abnormal STAT3 function is associated with cancer development and other diseases." (PMID 29543893, 2018). "Elevated IL-6 and IL-6-mediated activation of STAT3 have been reported to cause chemoresistance to several chemotherapeutic drugs, like cisplatin and taxol, in various cancers including OCs." (PMID 29050266, 2017). "The reports indicate that constitutive STAT3 activation is associated with anti-apoptotic as well as proliferative effects in various human cancers." (PMID 28282460, 2017). "For instanse, STAT3 plays an important role in both cancer cells and tumor-associated immune cells to promote cancer progression and survival with upregulation of BCL-XL protein expression." (PMID 28241765, 2017). "Many genes, such as Bcl-xl, kRAS, COX, iNOS, APC, Smad3, STAT3, Ptgs2, Tnfrsf6, p16, Mlh1, Runx3, Dapk, and β-catenin are mutated in stages of carcinogenesis of the UC-associated cancer." (PMID 28621756, 2017). "In normal cells, this feedback circuit contributes to the maintenance of cell homeostasis; in contrast, in cancer cells loss of PTPRD expression or function leads to STAT3 overactivation and promotion of tumorigenesis." (PMID 29228728, 2017). "The IL-6 driven STAT3 phosphorylation and activation in OxS has been shown before and has been linked with inflammation, cell injury, and cancer, but the potential role of SP-A2 in this process is novel." (PMID 29202868, 2017). "Several studies indicated a significant association between STAT3 expression and drug resistance in cancer." (PMID 28720093, 2017). "Signal transducer and activator of the transcription 3 (STAT3), whose constitutive activation is frequently detected in various human cancers including CRC, has been proposed as a pathogenic factor of CRC and a target for CRC treatment." (PMID 28503147, 2017).
cancer (continued). "Evidence suggests that the Janus kinase 2/signal transducer and activator of transcription 3 (Jak2/STAT3) signalling pathway is associated with oncogenesis and the progression and metastasis of different cancers." (PMID 27862996, 2017). "STAT3 inhibition in cancer cells appeared to be involved in the apoptotic process promoted by DHA, as STAT3 de-phosphorylation was associated with cancer cell death and treatment with a phosphatase inhibitor inhibited the cancer cell death." (PMID 28435516, 2017). "STAT3 is an important transcription factor for many cytokines and growth factor receptors, and it is associated with the maintenance of cancer stem cells." (PMID 29340087, 2017). "IL-6/Janus kinase 2 (Jak-2)/signal transducer and activator of transcription 3 (STAT3) pathway has been implicated as a key player in many cancer types." (PMID 28970500, 2017). "Accordingly, aberrant and persistent STAT3 phosphorylation is frequently observed in human epithelial origin cancers and is often associated with poor outcome." (PMID 28032598, 2017). "Constitutive activation of STAT3 is implicated in stem cell self-renewal, cancer cell survival, and inflammation in PDAC." (PMID 28374746, 2017). "Apurinic/apyrimidinic endonuclease/redox factor-1 (APE1/Ref-1) is a multifunctional protein that, in addition to its base excision DNA repair activity, exerts a redox control on cancer-associated transcription factors, including STAT3." (PMID 28489571, 2017). "In particular, STAT3 participates in the initiation, development, and progression of human cancers by inducing STAT3 downstream genes that encode anti-apoptotic proteins, cell cycle regulators, and angiogenic factors such as Bcl-xl and cyclin D1." (PMID 28187727, 2017). "Especially because constitutive STAT3 activation is associated with poor prognosis in cancer patients, STAT3 has been investigated as a cancer therapeutic target." (PMID 28245605, 2017). "Activation of two major inflammatory pathways, NF-κB and Signal transducer and activator of transcription 3 (STAT3), is associated with most cancers." (PMID 28946660, 2017). "STAT3 participates in the initiation, development, and progression of human cancers via inducing downstream genes that encode anti-apoptotic proteins, cell cycle regulators, and angiogenic factors such as Bcl-xl and cyclin D1." (PMID 28187727, 2017). "Persistent STAT3 activation has been linked with several chronic diseases, including various cancers." (PMID 28208828, 2017). "Activation of Signal Transducer and Activator of Transcription 3 (STAT3) has been linked to several processes that are critical for oncogenic transformation, cancer progression, cancer cell proliferation, survival, drug resistance and metastasis." (PMID 28636670, 2017). "After activation, JAK2 kinase can phosphorylate STAT3, which then translocates to the nucleus to enhance the levels of downstream genes, including anti-apoptotic genes that are implicated in human cancer development." (PMID 28570563, 2017). "Notwithstanding, the STAT3 Y640F mutation was already described as one of the most common STAT3 somatic mutations associated with the onset of several cancers, both hematological and solid." (PMID 29162862, 2017). "This notion is of particular interest as persistent STAT3 phosphorylation is a hallmark of several cancers and leads to the gene expression responsible for malignant cell proliferation and resistance to apoptosis, as well as increased invasion and migration." (PMID 28819544, 2017). "In primary tumors of OSCC patients, STAT3 is constitutively activated and induces expression of cyclin D1, which is associated with cancer cell growth." (PMID 28085115, 2017). "This pro-inflammatory cytokine is implicated in a milieu of cancer types because of its propensity to drive the activation of the oncogenic transcription factor signal transducer and activator of transcription 3 (STAT3)." (PMID 29371911, 2017).
cancer (continued). "Constitutive activation of STAT3 is involved in a wide range of human cancers and associated with tumorigenesis, therefore, STAT3 is regarded as a promising target for cancer therapy." (PMID 28455960, 2017). "IL-11 transmits signals through its unique receptor, IL-11Rα, which couples with the common receptor subunit GP130 to activate the downstream STAT3 signaling pathway, a pathway that is closely associated with cancer pathogenesis." (PMID 29100303, 2017). "The constitutive activation of STAT3 has been implicated in the regulation of cancer cell survival (survivin, Bcl-xL), proliferation (cyclin D1/D2) and anti-apoptosis (Bcl-2)." (PMID 28114390, 2017). "It has been demonstrated that the over-expression of PL2L60 in cancer cells is associated with up-regulation of STAT3 mRNAs." (PMID 28545024, 2017). "Many studies have shown that Stat3 plays oncogenic roles by promoting the expression of cancer-associated genes such as cyclinD1, c-Myc, Cox-2, and Bcl-2." (PMID 29245928, 2017). "STAT3 is constitutively activated in many human cancers with poor prognosis or chemo- or radio-resistance, which have been molecularly linked through cancer genome landscape studies to increased tyrosine kinase signaling in particular." (PMID 27259262, 2016). "STAT3 is rarely mutated in cancer and the (epi)genetic alterations that lead to STAT3 activation are incompletely understood." (PMID 27855189, 2016). "The IPA knowledge base suggested that the identified miR-373-associated molecules interconnected with STAT3 to a common signaling pathway, combining the overlapping functions “inflammation” and “invasion” in “cancer”." (PMID 27271572, 2016). "In a subset of cancer types, activating mutations of upstream kinases lead to persistent STAT3 pathway activation and predict response to kinase inhibition." (PMID 27855189, 2016). "Increased level of IL-6 was observed in prostatospheres compared with adherent bulk cancer cells and this was associated with stronger activation of STAT3." (PMID 27732936, 2016). "Attenuated STAT3 signaling pathway results in reduced levels of cyclinD1 and Bcl-2, which caused cancer cells being arrested in G1/S phases and ultimately apoptotic cell death." (PMID 27058422, 2016). "Constitutive activation of STAT3 has been observed in many cancers and has been linked to increased cell proliferation and survival." (PMID 27340780, 2016). "Constitutive STAT3 activation by tyrosine phosphorylation of mutated or amplified tyrosine kinases (pYSTAT3) is critical for cancer initiation, progression, invasion, and motility of carcinoma cells." (PMID 27259262, 2016). "The oncogenic transcription factor STAT3 is often constitutively activated in various types of human cancer, including MM, and is closely associated with cancer cell proliferation and anti-apoptosis." (PMID 26848618, 2016). "Additional evidence supporting a link between DFS70/LEDGFp75 and STAT3 came from studies demonstrating that switching the expression of STAT3 to STAT3β, its dominant negative truncated variant, in cancer cells led to DFS70/LEDGFp75 repression." (PMID 26088181, 2016). "STAT3 with PTEN is part of the positive feedback loop that underlies the epigenetic switch that links inflammation to cancer." (PMID 26762586, 2016). "More importantly, phosphorylation of STAT3 at Y705 was dispensable for the inhibition of apoptosis in bulk cancer cells by overexpression with S727E point-mutated STAT3, suggesting that the phosphorylation of S727STAT3 mediates suspension survival in TICs." (PMID 27306323, 2016). "Of note, there are six members in the STAT family of which STAT1, STAT3 and STAT5 are highly associated with cancer, but SC09 specifically inhibits STAT3 activation thus inducing cancer cell death." (PMID 27705908, 2016). "Inflammatory cytokines, NF-κB and Stat3 activation have been closely associated with cancer progression and CSC development." (PMID 26506421, 2016).
cancer (continued). "Of note, STAT3 signaling is not only important for cancer cells in antagonizing apoptosis but has also been reported to be associated with cancer EMT by STAT3 transcriptional activation of EMT inducers TWIST1 and ZEB1 involved in E-cadherin repression." (PMID 27580057, 2016). "The RAS/RAFMAPK and JAK/STAT3 signal pathways have been implicated with the resistance and survival of cancer cells." (PMID 26910118, 2016). "STAT proteins, especially STAT3, are crucial for both the extrinsic and the intrinsic pathways underlying cancer inflammation." (PMID 27690342, 2016). "Most interestingly, knockdown of Col17a1 reduced suspension survival in enriched TICs and in bulk cancer cells expressing S727E point-mutated STAT3." (PMID 27306323, 2016). "We then demonstrated that overexpression of S727A point-mutated STAT3 reduced Col17a1 expression in TICs, while overexpression of S727E point-mutated STAT3 increased Col17a1 expression in bulk cancer cells." (PMID 27306323, 2016). "STAT family proteins, particularly STAT3, are firmly implicated in the induction and maintenance of an inflammatory microenvironment that facilitates malignant transformation and cancer progression." (PMID 26972355, 2016). "Constitutive activation of Stat3 is implicated in a wide range of human cancers, which indicates that Stat3 is a target for cancer treatment." (PMID 27278358, 2016). "First, chronic inflammation per se is associated with the development of cancer, and, for example, prolonged IL-6 signaling and STAT3 activity is known to be pro-tumorogenic." (PMID 26788120, 2016). "STAT3 was frequently constitutively activated in many human cancers, and STAT3 activation was also associated with therapeutic drug resistance." (PMID 25963978, 2015). "JSI-124 has been reported to inhibit the proliferative activity of several types of cancer cells associated with apoptotic cell death mediated via the inhibition of the constitutively activated STAT3 signaling pathway." (PMID 25789853, 2015). "As a multifunctional cytokine, IL-6 has been implicated in the maintenance of stem cancer cells through the IL-6/gp130/STAT3 signaling pathway." (PMID 26631279, 2015). "It should be noted that in a previous study, the IL-32γ variant has been shown to inhibit cancer growth by silencing the NF-κB and STAT3 signaling pathways." (PMID 25435980, 2015). "STAT3 is predominantly activated by IL-6 receptor via JAK1/2 in cancer cell lines in association with transcriptional silencing of SOCS-1 by hypermethylation." (PMID 26491227, 2015). "Taken together these results indicate that PTPN6 mutations, N225K or A550V can deregulate STAT3 phosphorylation in cancer cells." (PMID 26565811, 2015). "The crosstalk between the STAT3 and NFκB signaling pathways is associated with cancer and inflammation." (PMID 26610525, 2015). "STAT3, in particular, is linked closely with cancer development via activation of immunomodulatory cytokines (IL-6, IL-10, and IL-17), growth factors (FGF, VEGF), and matrix metalloproteinases." (PMID 26538823, 2015). "The STAT3 pathway is associated with progression in several human cancers, and this is often reflected in STAT3 constitutive phosphorylation." (PMID 25861239, 2015). "Because STAT3 is associated with the metastatic behavior of cancer cells, wehypothesized that ASS1 suppression inhibits STAT3 expression in gastric cancercells." (PMID 25928182, 2015). "Our novel results suggest that the activated/phosphorylated Tyr705 of STAT3 (P-STAT3 Y705) promotes cancer cell survival and causes feed-back resistance to MEK inhibitors." (PMID 25961376, 2015). "An important mediator implicated in the development of cancer cachexia is the transcription factor STAT3 that previous work has shown activated by circulating pro-inflammatory cytokines (i.e. IL-6)." (PMID 25460504, 2015).